OR9H1 (olfactory receptor family 9 subfamily H member 1 (gene/pseudogene))
Description:
Odorant receptor.
Synonyms: OR9H1P; UNQ9373
Gene: Protein-coding gene on chromosome 1 (247,770,169 to 247,779,524, forward strand). Ensembl gene ENSG00000228336.
Subcellular location: Cell membrane
Homologues: Orthologues: chimpanzee OR9H1P (99% identical), macaque OR9H1P (89% identical), mouse Or9s18 (84% identical), rat Or9s18 (84% identical), rabbit OR9H1 (76% identical), guinea pig OR9H1 (72% identical). Paralogues in human: OR5AP2 (55% identical), OR5AR1 (54% identical), OR5B21 (54% identical), OR5D18 (54% identical), OR9I1 (52% identical), OR5J2 (52% identical), OR5W2 (51% identical), OR9G4 (51% identical), OR5A1 (50% identical), OR5I1 (50% identical), OR9K2 (50% identical), OR5L1 (50% identical), and 84 more.